SLC14A2 (solute carrier family 14 member 2)
Description:
[Isoform 1]: Mediates the transport of urea driven by a concentration gradient across the cell membrane of the renal inner medullary collecting duct which is critical to the urinary concentrating mechanism. [Isoform 2]: Mediates the transport of urea driven by a concentration gradient across the cell membrane of the kidney inner medullary collecting duct which is critical to the urinary concentrating mechanism.
Synonyms: HUT2; UT2; UT-A2; UTA; UTR; hUT-A6
Tractability: Small molecule: a structure with a bound ligand is known. Antibody: UniProt places it where antibodies can reach, with high confidence; its Gene Ontology location is reachable by antibodies, with high confidence; UniProt predicts a signal peptide or a membrane-spanning region. PROTAC: ubiquitination databases record sites on it.
Gene: Protein-coding gene on chromosome 18 (45,212,995 to 45,683,688, forward strand). Ensembl gene ENSG00000132874.
Subcellular location: Apical cell membrane (Isoform 1); Cell membrane
Pathways (Reactome):
Transport of small molecules: SLC-mediated transport of organic cations
Gene Ontology:
Molecular function: cell adhesion molecule binding; protein binding; urea transmembrane transporter activity
Biological process: amine transport; urea transmembrane transport; urea transport
Cellular component: apical plasma membrane; plasma membrane; membrane
Genetic constraint (gnomAD): Loss-of-function variants: 86 observed, 102.09 expected, observed/expected ratio (o/e) 0.84, 90% interval 0.71 to 1.01. The upper end of that interval is the gene's LOEUF score, 1.01, which puts it in group 4 of 6, group 1 being the genes least tolerant of losing a copy. Missense variants: 1,157 observed, 1,174.3 expected, observed/expected ratio (o/e) 0.99, 90% interval 0.94 to 1.03. Synonymous variants: 466 observed, 475.8 expected, observed/expected ratio (o/e) 0.98, 90% interval 0.91 to 1.06.
Homologues: Orthologues: chimpanzee SLC14A2 (99% identical), macaque SLC14A2 (96% identical), pig SLC14A2 (86% identical), rat Slc14a2 (86% identical), rabbit SLC14A2 (82% identical), mouse Slc14a2 (40% identical), dog SLC14A2 (38% identical), tropical clawed frog slc14a2 (29% identical), zebrafish slc14a2 (25% identical). Paralogues in human: SLC14A1 (26% identical).
Diseases named in the same sentence as SLC14A2 in open-access papers:
SLC14A2 is named in the same sentence as 14 diseases in open-access papers, as found by Europe PMC text mining. Sharing a sentence is not in itself a finding about the gene and the disease. The quoted sentences say what the papers report.
breast carcinoma (2 papers, 2023 to 2025). "Additionally, according to TCGA data, rs9952980 was found to be significantly associated with reduced SLC14A2 expression in breast cancer patients, likely mediated by its direct impact on ESR1-DNA binding." (PMID 41301792, 2025). "Two intronic AIMs (rs13267382: chr8, LINC00536; rs9952980: chr18, SLC14A2) and two intergenic AIMs (rs10832963: chr11, SPTY2D1 - SRSF3P1; rs11814448: chr10) were also found to be associated with breast cancer in samples of European and Asian ancestry." (PMID 36911410, 2023).
Hypertension (1 paper, 2018). The presence of chronic increased pressure in the systemic arterial system. "rs1484873 and rs7232775 in SLC14A2 on chromosome 18 were also associated with BUN and hypertension." (PMID 29558500, 2018).
ovarian carcinoma (1 paper, 2018). A malignant neoplasm originating from the surface ovarian epithelium. "Furthermore, SLC14A2, which was significantly higher in both BoAA and Caucasian tumours compared to Asian cases has been shown to be down-regulated in chemotherapy-resistant ovarian cancer cell lines, suggesting potential race-specific targets for treatment." (PMID 29682207, 2018).
tumor (4 papers, 2013 to 2025). "SLC14A2 has been reported to have 9 tumor-associated SNPs, which are associated with susceptibility to various tumors." (PMID 41301792, 2025). "Additionally, SLC14A2 is associated with the tumor immune microenvironment." (PMID 41301792, 2025). "SLC14A2 (solute family 14, member A) is a urea transporter normally expressed in the renal epithelium has not previously been associated with malignancy but may have a role in the efflux of toxic metabolites from the tumor cells." (PMID 26893359, 2016). "There is relatively limited research on SLC14A2 in tumors, but it has been identified as a drug sensitivity gene that can be utilized in some anti-tumor drug screening studies." (PMID 41301792, 2025). "Moreover, the mutations ALPK2.R136S, CHST9.S122N, FAM38B.V2463, LAMA1.S1577A, LAMA1.K2002E, MYOM1.T215M, SERPINB10.R246C and SLC14A2.A880T were found in all three tumor samples and shared a similar frequency profile." (PMID 23892400, 2013).
SLC14A2 also shares sentences with these, for which no sentence is quoted: cancer (2 papers); lung carcinoma (2); bladder cancer (1); epilepsy (1); esophageal squamous cell carcinoma (1); follicular lymphoma (1); frontotemporal dementia (1); infection (1); neurofibromatosis (1); nicotine addiction (1).